IL2 (interleukin 2)
Diseases named in the same sentence as IL2 in open-access papers (continued):
Sharing a sentence is not in itself a finding about the gene and the disease.
cervical carcinoma (44 papers, 1999 to 2025). A carcinoma arising from either the exocervical squamous epithelium or the endocervical glandular epithelium. "Nevertheless, our workgroup reported that treatment with 100 IU of IL-2 induces a decrease in the phosphorylation of proteins involved in the proliferation of cervical cancer cells, which potentially causes a reduction in cell proliferation." (PMID 31662754, 2019). "Decreased natural killer (NK) activity as well as interleukin 2 (IL-2) are risk factors for the progression of cervical carcinoma." (PMID 9888464, 1999). "Furthermore, cytokine release (TNF-α, IFN-γ, and IL-2), which is a hallmark of T-cell activation upon tumor cell lysis, was also induced by TF-BiTE in cervical cancer cell lines." (PMID 41009508, 2025). "Although interleukin-2 (IL-2) has long been associated with cancer development, its roles in the development of cervical cancer remains unclear." (PMID 37256111, 2023). "Cervical cancer risk in smokers may be modified by genetic variants, as that described to interleukin 2 or to 8q24 chromosome polymorphisms." (PMID 21785734, 2011). "Both strategies demonstrated enhanced cytotoxicity in preclinical models, and early clinical data suggest that targeting T cell exhaustion (e.g., GT316) or cytokine signaling (e.g., GT201) may overcome barriers such as IL-2 deficiency or T cell dysfunction in the cervical cancer TME." (PMID 40458394, 2025). "This also opens the way for new immunotherapy modalities such as systemic use of low dose of IL2.Therabuticallly, IL-2 has also been explored in cervical cancer immunotherapy models where it enhanced engineered T-cell efficacy." (PMID 41408300, 2025). "Recent studies have highlighted that IL-2 stimulates the proliferation of neoplastic cells in cervical cancer." (PMID 40142865, 2025). "Various types of different liposomal formulations, including cationic, anionic, and neutral liposomes, have been explored for delivering IL-2 to cervical cancer cells, with CLs demonstrating high affinity for cancer cells and enhanced IL-2 cytotoxicity." (PMID 40143046, 2025). "By simultaneously activating the CD95 and IL-2 signalling pathways, a cytoprotective mechanism leads to cervical cancer cell survival." (PMID 39766250, 2024). "CD95 is not the only molecule associated with a pleiotropic response; our work group has shown that IL-2 can also have a differential effect on cervical cancer cells." (PMID 39766250, 2024). "The cervical cancer cell lines HeLa and SiHa increased their proliferation with 10 UI/mL of IL-2; however, when treated with 100 UI/mL, proliferation decreased." (PMID 38999946, 2024). "On the other hand, our work group showed that IL-2 can also be used in an autocrine manner by cervical cancer cells to promote their proliferation." (PMID 39766250, 2024). "Since IL-2 induces a response in cervical cancer cells, we evaluated the tyrosine phosphorylation of STAT5 in the cell line SiHa due to its higher expression of STAT5." (PMID 38999946, 2024). "Another relevant molecule in the control of the immune response is IL-2, which we have previously reported to have a differential effect on cervical cancer cell lines." (PMID 39766250, 2024). "Our results show that IL-2 induces cervical cancer cell proliferation and the tyrosine phosphorylation of STAT5." (PMID 38999946, 2024). "Recent reports have also demonstrated that changes in IL-2 levels play an important role in the development and progression of cervical cancer." (PMID 37256111, 2023). "Second, an objective assessment of IL-2 levels, high-risk HPV, and other cervical cancer-related clinical examinations such as Pap test colposcopy, and cervical biopsy was conducted." (PMID 37256111, 2023). "An essential function of IL-2 and its receptor has been reported in breast and cervical cancer growth, correlating malignancy of the tumor and expression of this receptor." (PMID 37372319, 2023).
cervical carcinoma (continued). "As a multi-effect immune factor resisting cervical cancer, IL-2 is secreted by innate killing cells, macrophages, and auxiliary T lymphocytes." (PMID 37383719, 2023). "Cervical cancer and other tumors also secrete cytokine IL-2, which plays an immune escape role in the tumor microenvironment and is an essential factor for maintaining the growth of tumor cells." (PMID 36726132, 2023). "Recent studies, have shown their efficient applicability in cervical cancer when combined with cisplatin (lipoplatin), paclitaxel, interleukin 2 (IL-2), and curcumin." (PMID 35571568, 2022). "Results showed that the expression profiles of cytokines detected in the two cervical cancer cell lines were consistent and IL‐2, IL‐4, IL‐6, IL‐8, IFN‐γ, MCP‐1 and TNF‐α were all expressed." (PMID 31943744, 2020). "It has been reported that the soluble sIL2Rα, an antagonist of IL2 signaling, is elevated in response to disease severity in cervical cancer patients, whereas IL2 levels declined with disease severity." (PMID 33050319, 2020). "Surprisingly, treatment with IL-2 protects the cervical cancer cell line INBL from entering apoptosis induced by cisplatin." (PMID 31662754, 2019). "IL-2 decreases cervical cancer cell proliferation via transient arrest of the G1 phase, which does not result in apoptosis or senescence." (PMID 31662754, 2019). "Anionic liposomes were found to be cytotoxic upon co-culturing with cervical cancer cell line, and neutral, cationic liposomes were identified by using a fluorescent anti-IL-2 antibody." (PMID 30410707, 2017). "The humanized CD47-CAR-T cells also specifically killed ovarian, pancreatic, and cervical cancer cell lines and produced IL-2 that correlated with expression of CD47." (PMID 29065481, 2017). "The expression of IL-2R and the production of IL-2 in cervical cancer cells have been documented as well as expression of molecules of the JAK-STAT pathway." (PMID 27293315, 2016). "High doses of IL-2 may have similar effects to those of nicotinamide inhibitors by decreasing cervical cancer proliferation." (PMID 38999946, 2024). "We further evaluated whether pre-treatment with high and low doses of IL-2 affects the response of cervical cancer cells to stimulation with anti-CD95 agonist antibodies." (PMID 39766250, 2024). "Some reports indicated that STAT5 activation is related to a metabolic shift; since we found that the cervical cancer cell line SiHa expressed the IL-2R and responded to exogenous IL-2 via STAT5, we determined the effect of different IL-2 concentrations (10 and 100 IU/mL) on the NAD+/NADH ratio." (PMID 38999946, 2024). "In addition, we have observed that the cervical cancer cell line C33A (HPV-negative) also responds to low doses of IL-2, increasing its proliferation, and to high doses, which decrease it (manuscript in preparation)." (PMID 39766250, 2024). "All of this background led us to analyse the CD95 and IL-2 pathways in cervical cancer cells and determine whether they could have similar behaviour or whether the treatment of both pathways could enhance the activation of apoptosis or the autophagy pathway." (PMID 39766250, 2024). "On the other hand, the secreted lactate induced by 10 IU of IL-2 in cervical cancer cell line SiHa increased, in contrast to the decrease in lactate production induced by 100 IU/mL of IL-2 showing a dose-dependent effect, which was similar to that obtained in cell proliferation." (PMID 38999946, 2024). "The exact associations between IL-2 levels and high-risk HPV infection in the vaginal microenvironment with the development of cervical cancer remains unclear." (PMID 37256111, 2023). "It is unclear whether IL-2 and high-risk HPV have synergistic effects in the development of CIN and cervical cancer." (PMID 37256111, 2023).
cervical carcinoma (continued). "Studies have shown that IL-2 inhibits the proliferation of cervical cancer cells at high doses." (PMID 37256111, 2023). "Considering that IL-2 leads to a reduction in cell proliferation and possibly apoptosis, the current investigation was undertaken to evaluate the effect of IL-2 on the inhibition of proliferation of cervical cancer cells and to determine if this inhibition is due to an induction of cell death." (PMID 31662754, 2019). "Actually, IL10 is used in combination with IL2 in the treatment of cervical cancer." (PMID 30622662, 2018). "Therefore, it is necessary to analyse the response of lymphocytes and cervical cancer cells treated with different concentrations of IL-2." (PMID 27293315, 2016). "Therefore, a more detailed inspection of IL-2 signalling in cancer cells will aid in our understanding of the specific effects on this cytokine on cervical cancer cells." (PMID 27293315, 2016). "HMGB1, forkhead/winged helix transcription factor p3 (Foxp3), IL-2, and IL-10 protein expression was analyzed in 100 cervical tissue samples including cervical cancer, cervical intraepithelial neoplasia (CIN), and healthy control samples using immunohistochemistry." (PMID 24837834, 2014). "The administration of low doses of IL-2 might therefore be a valid therapeutic option in order to increase IDCC in heavily pretreated cervical carcinoma patients." (PMID 21693061, 2011). "This suggests that in cervical cancer patients’ vaginal microbiota, there’s a reduction in bacteria beneficial for anti-tumor immunity, while the abundance of Gardenerella, which inversely correlates with the expression of inflammatory factors IL2/IL12, significantly increases." (PMID 38881859, 2024). "However, when cervical cancer cells are stimulated with high doses of IL-2 and subsequently with anti-CD95 agonist antibodies at a concentration that induces proliferation, we observed that proliferation is recovered, that is, the inhibition induced by IL-2 is lost." (PMID 39766250, 2024). "Thus, the specific role of IL-2 is also being explored in cervical cancer." (PMID 37256111, 2023). "The poor prognosis in cervical cancer patients with elevated IL2Rα as part of the senescence phenotype may be explained by a lack of Th1 response as the consequence of immune suppression through sequestering free IL2." (PMID 33050319, 2020). "However, in cervical cancer cells, the mechanism that IL-2 activates to induce a decrease in cell proliferation is unknown." (PMID 31662754, 2019). "However, the role of IL-2 in cervical cancer is not fully understood." (PMID 27293315, 2016). "Recently, several reports indicate that STAT5 participates in metabolism regulation, and our workgroup has demonstrated that cervical cancer cells express STAT5, and its phosphorylation increased in response to IL-2." (PMID 38999946, 2024). "Previously, we demonstrated that cervical cancer cell lines CALO and INBL (HPV18+) expressed the transcription factor STAT5 and are phosphorylated in response to IL-2." (PMID 38999946, 2024). "On the other hand, we previously demonstrated that HPV18+ cervical cancer cell lines (CALO, INBL, and HeLa) can respond differentially to treatment with low and high concentrations of IL-2, inducing or inhibiting their proliferation, respectively." (PMID 39766250, 2024). "Altogether, our results indicate that IL-2 increases lactate production and the NAD+/NADH ratio in cervical cancer cells, which is consistent with aerobic glycolysis." (PMID 38999946, 2024). "Here, we determined the role of IL-2 in the induction of aerobic glycolysis by measuring lactate secretion, the NAD+/NADH ratio and the role of STAT5 in these metabolic responses in the cervical cancer cell line SiHa." (PMID 38999946, 2024). "When IL-2 binds to its receptor, it is followed by the activation of STAT5 in cervical cancer cell lines." (PMID 37372319, 2023).
cervical carcinoma (continued). "Previous studies had shown that secretion of pro-inflammatory cytokines, including IL-2 and IFN-γ, is observed in macrophage activation and then induced anti-tumor activity on human cervical cancer cells." (PMID 34635698, 2021). "Our workgroup reported that treatment with 100 IU of IL-2 induces a decrease in the phosphorylation of JAK3 and STAT5 proteins involved in the proliferation of cervical cancer cells." (PMID 31662754, 2019). "However, the effect of IL-2 on cervical cancer cells is unknown." (PMID 31662754, 2019). "To validate this, we applied the HPV peptide stimulation protocol with 150 U/ml IL-2 to blood samples, obtained before radical surgery, from eight HPV16+ cervical cancer patients." (PMID 27619514, 2016). "The levels of IL-1beta, IL-2, TNF-alpha, and IL-10 were negatively correlated with the percentages of CD4+NKG2D+ T cells in patients with cervical carcinoma." (PMID 26486970, 2015). "In cervical cancer, HPV-specific CD4+ T cells suppress cytokine (IFN-γ, IL-2) production to interfere with the anti-tumor immune response." (PMID 24465869, 2014). "Notably, treatment with CM derived from breast and cervical cancer cell lines, that is, KPL4 and Hela cells, led to a significant reduction in IL‐2 mRNA expression in activated Jurkat T cells compared with that in the untreated control." (PMID 39932384, 2025). "As a result, both PRME extract and puerarin showed a pattern of reducing various proinflammatory cytokine levels, including IL-2, IL-12, IFN-γ, and TNF-α, in HeLa cells, thereby proving that the PRME extract and puerarin also have anti-inflammatory effects in human cervical cancer cells." (PMID 39941110, 2025). "Thus, low doses of IL-2 induce high levels of NAD+, promoting high proliferation and metabolic flux in cervical cancer cells." (PMID 38999946, 2024). "The activity of NK and CTL is decreased in the absence of IL-2, promoting the development of tumors including cervical cancer." (PMID 37256111, 2023). "In hrHPV-induced cervical cancer and HNSCC, expression of immunostimulatory T helper 1 (Th1) cytokines such as interleukin 2 (IL-2), IL-12, tumor necrosis factor α (TNF-α), and IFNs is downregulated, whilst Th2 proinflammatory and immunosuppressive cytokines are overexpressed." (PMID 37112681, 2023). "IL-2 evaluation, as an adjuvant for an E7 DNA vaccine against HPV-16-related cervical cancer, suggested the potential of this immunoregulatory cytokine in higher infiltration, activation, and degranulation of CD8+ T cells, determined by an increase in IFN-γ and CD107a levels." (PMID 35752792, 2022). "In HPV-infected patients, the level of IL-2 in the peripheral blood of patients with cervical cancer is significantly lower than that in women without cervical lesions." (PMID 31297140, 2019). "Low doses of interleukin-2 further increased the cytotoxic effect induced by hI-con1 (p = 0.025) while human serum did not significantly decrease IDCC against cervical cancer cell lines (p = 0.597)." (PMID 21693061, 2011). "The role of IL-2 in the development of CIN and cervical cancer remains unclear." (PMID 37256111, 2023). "In an ongoing phase II study (NCT03108495), which is currently recruiting patients, autologous TILs followed by IL-2 after a non-myeloablative lymphodepletion preparative regimen are being tested in patients with recurrent, metastatic or persistent cervical carcinoma." (PMID 32455616, 2020). "For example, vectors could be used to carry high concentrations of IL-2 to the tumour cells without targeting normal lymphocytes to aid in the treatment of cervical cancer." (PMID 27293315, 2016). "JAK3 alone may be capable of initiating the signals induced by IL-2 even if JAK1 is not activated in cervical cancer cells." (PMID 27293315, 2016). "In cervical cancer, the aberrant expression of molecules is not restricted to IL-2 or IL-2R." (PMID 27293315, 2016).
cervical carcinoma (continued). "Treating cells with high doses of IL-2 inhibits cell proliferation, and simultaneous treatments with high doses of IL-2 and anti-CD95 agonist antibodies revert cell inhibition and increase LC3B foci in cervical cancer cells, but do not induce apoptosis." (PMID 39766250, 2024). "Independent or simultaneous treatment with IL-2 and low concentrations of the anti-CD95 agonist antibody in HeLa and SiHa cervical cancer cells did not impact the increase in apoptotic cells." (PMID 39766250, 2024).